TM9SF1 (transmembrane 9 superfamily member 1)
Description:
Plays an essential role in autophagy.
Synonyms: hMP70; MP70
Tractability: Antibody: UniProt predicts a signal peptide or a membrane-spanning region. PROTAC: ubiquitination databases record sites on it; its protein half-life has been measured.
Gene: Protein-coding gene on chromosome 14 (24,189,140 to 24,196,287, reverse strand). Ensembl gene ENSG00000100926.
Subcellular location: Lysosome membrane; Cytoplasmic vesicle, autophagosome membrane
Subcellular location (Human Protein Atlas): Golgi apparatus
Gene Ontology:
Biological process: protein localization to membrane
Cellular component: membrane; autophagosome membrane; lysosomal membrane
Genetic constraint (gnomAD): Loss-of-function variants: 25 observed, 55.37 expected, observed/expected ratio (o/e) 0.45, 90% interval 0.33 to 0.63. The upper end of that interval is the gene's LOEUF score, 0.63, which puts it in group 2 of 6, group 1 being the genes least tolerant of losing a copy. Missense variants: 604 observed, 819.91 expected, observed/expected ratio (o/e) 0.74, 90% interval 0.69 to 0.79. Synonymous variants: 284 observed, 316.96 expected, observed/expected ratio (o/e) 0.9, 90% interval 0.81 to 0.99.
Homologues: Orthologues: chimpanzee TM9SF1 (100% identical), macaque TM9SF1 (99% identical), pig TM9SF1 (98% identical), mouse Tm9sf1 (98% identical), rat Tm9sf1 (97% identical), rabbit TM9SF1 (97% identical), guinea pig TM9SF1 (97% identical), tropical clawed frog tm9sf1 (78% identical), dog TM9SF1 (78% identical), zebrafish tm9sf1 (72% identical). Paralogues in human: TM9SF3 (33% identical), TM9SF4 (33% identical), TM9SF2 (31% identical).
Diseases named in the same sentence as TM9SF1 in open-access papers:
TM9SF1 is named in the same sentence as 18 diseases in open-access papers, as found by Europe PMC text mining. Sharing a sentence is not in itself a finding about the gene and the disease. The quoted sentences say what the papers report.
gastric cancer (6 papers, 2022 to 2024). A primary or metastatic malignant neoplasm involving the stomach. "Furthermore, lower expression of TM9SF1 was significantly associated with poor overall survival of gastric cancer patients." (PMID 35597784, 2022). "For example, PCIF1 is involved in gastric cancer progression by inhibiting the mRNA translation of the tumor suppressor gene TM9SF1 via m6Am modification." (PMID 39451207, 2024). "PCIF1 can modify TM9SF1 mRNA through m6Am and inhibit its mRNA translation, thus reducing the level of TM9SF1 protein, thereby promoting the development of gastric cancer." (PMID 37779183, 2023). "Taken together, these data indicate that TM9SF1 is a functional downstream target of PCIF1 during gastric cancer development." (PMID 35597784, 2022). "The reduction of TM9SF1 protein in gastric cancer tissues predicts an unfavorable outcome for patients." (PMID 35597784, 2022). "Multivariate COX analysis revealed that TM9SF1 expression was an independent favorable predictor for clinical outcome of gastric cancer patients." (PMID 35597784, 2022). "In our study, we discover that TM9SF1 is a previously undescribed tumor suppressor gene in gastric cancer." (PMID 35597784, 2022). "Future studies will be clearly needed to determine how TM9SF1 influences the behaviors of gastric cancer cells." (PMID 35597784, 2022). "Mechanically, PCIF1 modifies TM9SF1 mRNA with m6Am to inhibit its mRNA translation, which reduces the protein levels of TM9SF1 to enhance gastric cancer cell malignancy." (PMID 35597784, 2022). "PCIF1 was involved in aggressiveness of gastric cancer cells via suppression of TM9SF1 mRNA translation." (PMID 36003776, 2022). "We silenced TM9SF1 in PCIF1-depleted gastric cancer cells with two independent shRNAs, and found that knockdown of TM9SF1 significantly reversed the inhibitory effects of PCIF1 depletion on cell invasion and cell proliferation." (PMID 35597784, 2022). "Taken together, these data indicate that TM9SF1 is a tumor suppressor of gastric cancer and predicts a favorable survival of patients." (PMID 35597784, 2022). "To characterize the function of TM9SF1 in gastric cancer development, we forced to express TM9SF1 in gastric cancer cells, and found ectopic TM9SF1 significantly inhibited cell proliferation and invasion." (PMID 35597784, 2022). "Furthermore, knockdown of TM9SF1 reverses the decreased malignancy induced by PCIF1 deletion in gastric cancer cells." (PMID 35597784, 2022). "TM9SF1 reverses the effects of PCIF1 on gastric cancer cell aggressiveness." (PMID 35597784, 2022). "Ectopic expression of TM9SF1 attenuates the aggressiveness of gastric cancer cells." (PMID 35597784, 2022). "To explore whether TM9SF1 plays a role in gastric cancer progression, we tested the expression of TM9SF1 by tissue array analysis." (PMID 35597784, 2022). "Together, these data imply that TM9SF1 may play a tumor suppressor role in gastric cancer." (PMID 35597784, 2022). "In gastric cancer, PCIF1 suppresses TM9SF1 mRNA translation, contributing to tumor aggressiveness and metastasis." (PMID 37643007, 2023). "Considering PCIF1 was frequently upregulated in gastric cancer tissues, we overexpressed PCIF1 and found that the relative proportion of modified TM9SF1 mRNA was robustly increased to more than 70% in AGS cells." (PMID 35597784, 2022). "The results showed that TM9SF1 was significantly downregulated in gastric cancer tissues compared with their paired non-tumor tissues." (PMID 35597784, 2022). "Moreover, we found that TM9SF1 (transmembrane 9 superfamily member 1) is a functional mRNA target of PCIF1 and acts as a tumor suppressor gene in gastric cancer." (PMID 35597784, 2022). "Since PCIF1 is associated with gastric cancer aggressiveness and suppresses TM9SF1 mRNA translation, we continued to determine whether TM9SF1 mediates the oncogenic role of PCIF1 in gastric cancer progression." (PMID 35597784, 2022).
breast carcinoma (3 papers, 2018 to 2025). "Recent bioinformatics studies show that TM9SF1 is a tumor-associated antigen of breast cancer and a prognostic marker for cervical cancer." (PMID 35597784, 2022). "In breast cancer, TM9SF1 has been identified by screening cancer specific antigens that are potentially applied to immunotherapy." (PMID 29362448, 2018). "In this study, TM9SF1 was overexpressed in breast cancer tissues compared with normal breast." (PMID 29362448, 2018).
prostate carcinoma (3 papers, 2018 to 2022). A carcinoma that arises from epithelial cells of the prostate gland. "To investigate the role of TM9SF1 in prostate cancer cells, we performed functional studies using siRNA targeting TM9SF1 (siTM9SF1) in LNCaP cells." (PMID 29362448, 2018). "TM9SF1 has also been reported to interact with EBAG9 (estrogen receptor binding site associated antigen 9) and be involved in epithelial–mesenchymal transition process of prostate cancer cells." (PMID 35597784, 2022). "TM9SF1 and EBAG9 cooperatively regulate prostate cancer cell migration by modulating the expression of genes involved in epithelial-mesenchymal transition (EMT)." (PMID 29362448, 2018). "In prostate cancer cells, EBAG9 regulated cell migration and EMT-related gene expression through the interaction with TM9SF1." (PMID 29362448, 2018).
urinary bladder cancer (3 papers, 2011 to 2022). A primary or metastatic malignant neoplasm involving the bladder. "In addition, TM9SF1 has been found to be increased in urinary bladder cancer by microarray analysis." (PMID 35597784, 2022).
cervical cancer (2 papers, 2019 to 2020). A primary or metastatic malignant neoplasm involving the cervix. "TM9SF1 plays an essential role in autophagy, and its expression is reported to have a significant role in AS associated prognosis prediction in cervical cancer patients." (PMID 33160404, 2020). "Four characteristic genes, HSPA14, SDHAF2, CAMKK2 and TM9SF1, that can be used as prognostic markers for cervical cancer were selected." (PMID 31744495, 2019). "In our study, high expression of TM9SF1 worsened prognosis in cervical cancer." (PMID 33160404, 2020).
colorectal cancer (2 papers, 2024 to 2025). A primary or metastatic malignant neoplasm that affects the colon or rectum. "In this study, we report that transmembrane 9 superfamily member 1 (TM9SF1) suppresses colorectal cancer metastasis via selective autophagic degradation of Vimentin." (PMID 40175707, 2025). "Tm9sf1 knockout significantly increases tumor numbers and size, as well as enhances tumor invasion in colorectal cancer model." (PMID 40175707, 2025). "In vitro and in vivo phenotypical analyses reveal that TM9SF1 functions as a metastasis suppressor in colorectal cancer." (PMID 40175707, 2025). "Moreover, TM9SF1 is downregulated in colorectal cancer patients with advanced stage compared to those with early stage and associated with favorable prognosis." (PMID 40175707, 2025).
corneal disease (1 paper, 2019). "TM9SF1 is an autophagy-induced gene that has been shown to be associated with Fuchs’ endothelial dystrophy and corneal disease." (PMID 31744495, 2019).
esophageal cancer (1 paper, 2022). A primary or metastatic malignant neoplasm involving the esophagus. "Furthermore, we found two marker genes (TM9SF1, PDZK1IP) directly related to the OS of esophageal cancer." (PMID 35299644, 2022).
intracranial aneurysms (1 paper, 2024). "TM9SF1 has also been linked to a range of other conditions, including certain tumors, ruptured intracranial aneurysms, and varicose spermatic veins." (PMID 38887291, 2024).
lung injury (1 paper, 2024). "Work from our group recently unveiled an increase in TM9SF1 expression levels in the lungs of mice suffering from LPS-induced acute lung injury, while TM9SF1 knockdown in these animals was found to alleviate the pulmonary inflammation induced by LPS through the enhancement of autophagic activity." (PMID 38887291, 2024). "TM9SF1 is a TM9SF family protein with 9 transmembrane domains and a large non-cytoplasmic region, and its expression at the mRNA level is altered in a mouse model of lipopolysaccharide (LPS)-induced acute lung injury." (PMID 38887291, 2024).
squamous cell cervical cancer (1 paper, 2020). "Next, we carried out multivariate Cox regression analysis and identified 6 genes (ATG3, BCL2, CD46, IFNG, NAMPT, TM9SF1) that were independently associated with OS in squamous cell cervical cancer patients." (PMID 33160404, 2020). "After univariate and multivariate Cox regression assay of differentially expressed ARGs, 6 ARG (ATG3, BCL2, CD46, IFNG, NAMPT, TM9SF1) related prognostic signatures for squamous cell cervical cancer were constructed." (PMID 33160404, 2020).
tumor (7 papers, 2018 to 2025). "Our result indicated that exogenic expression of TM9SF1 in PDX-GC cells obviously inhibited tumor metastasis." (PMID 35597784, 2022). "The result showed that exogenous expression of TM9SF1 in PDX cells significantly inhibited tumor growth." (PMID 35597784, 2022). "TM9SF1 can bind to the estrogen receptors, regulate the epithelial-mesenchymal transformation of cancer cells, and promote tumor metastasis." (PMID 34257653, 2021). "We propose that the EBAG9 interactor TM9SF1 may cooperatively function in the EBAG9-mediated tumor-promoting effects." (PMID 29362448, 2018).
cancer (4 papers, 2018 to 2024). A tumor composed of atypical neoplastic, often pleomorphic cells that invade other tissues. "In mammals, four members of this protein family (TM9SF1–4) have thus far been identified, with a limited number of prior reports having documented the relationships between these proteins and certain cancers." (PMID 38887291, 2024). "Although TM9SF1 is ubiquitously expressed in various normal tissues, TM9SF1 overexpression is reported in several cancers." (PMID 29362448, 2018). "While the mechanism of TM9SF1 remains to be elusive, we speculate that EBAG9 and TM9SF1 could cooperatively regulate cancer cell migration." (PMID 29362448, 2018). "We identified TM9SF1 as a collaborative EBAG9 interactor, which regulates epithelial-mesenchymal transition (EMT) in cancer cells." (PMID 29362448, 2018).
TM9SF1 also shares sentences with these, for which no sentence is quoted: bladder cancer (1 paper); COVID-19 (1); diabetes (1); Fuchs' endothelial dystrophy (1); head and neck squamous cell carcinoma (1).